KAT2B (lysine acetyltransferase 2B)
Diseases named in the same sentence as KAT2B in open-access papers (continued):
Sharing a sentence is not in itself a finding about the gene and the disease.
cancer (84 papers, 2002 to 2025). A tumor composed of atypical neoplastic, often pleomorphic cells that invade other tissues. "The expression of most BrD members significantly negatively correlated with cancer stemness across many TCGA tumor types, although only for KAT2B, KMT2A, SMARCA2, BAZ2B, SP100 and SP140, the association was highly consistent (regardless of the tumor type)." (PMID 35049055, 2022). "The association of KAT2B with cancer progression/cell cycle was also shared by SGOL, ROBO1, and ICK, and represents the only functional overlap with genes identified with persistent and intermittent carriage of S. aureus." (PMID 26569114, 2015). "Since our experimental data indicated that KAT2B was associated with metastatic ability of cancer phenotypes, we next exploited whether KAT2B could regulate tumor metastasis markers expression." (PMID 34130593, 2021). "In addition, KAT2B has been linked to immune function, cancer progression, and adipogenesis." (PMID 26569114, 2015). "Lysine acetyltransferase 2B (KAT2B) is a known histone acetyltransferase epigenetic factor, which is involved in the proliferation and DNA damage of cancer cells." (PMID 39901144, 2025). "KAT2B-related acetylation of EZH2 blocks its ability for target gene regulation, resulting in cancer progression, and is associated with poor survival." (PMID 37887281, 2023). "To investigate the functional consequences of KAT2B ablation on EMT and cancer stemness, we depleted KAT2B in the Dox-induced MCF7ras+SS cells." (PMID 37117180, 2023). "HDAC3, HDAC10, HDAC2, HDAC7, ATAD2B were significantly upregulated in 9, 14, 13, 9, and 10 cancer types, respectively, whereas KAT2B was downregulated in 16 cancer types." (PMID 37553641, 2023). "In contrast, KAT2B overexpression correlates negatively with cancer de-differentiation status, which is in line with the previously reported role of KAT2B in mediating differentiation of normal multipotent progenitor cells." (PMID 36674511, 2023). "Particularly, KAT2B was downregulated in all five cancers as well as in approximately 3000 other cancer samples." (PMID 35422864, 2022). "A number of bromodomain genes are consistently decreased in the TCGA cancer dataset, including KAT2B, SMARCA2, zinc finger MYND domain-containing protein 11 (ZYMND11), and mixed-lineage leukemia (MLL)." (PMID 34298819, 2021). "For example, a previous study indicates that KAT2B induces H3K9Ac on the Gli1 target gene promoters in order to induce cell proliferation in cancer cells." (PMID 30305648, 2018). "Kat2a and Kat2b regulate various physiological phenomenon, including embryonic development, brown adipogenesis, transcription, genome stability, cancer, immune response, and angiogenesis." (PMID 30424580, 2018). "The targeting and inhibition of KAT2B also inhibit cancer by a variety of mechanisms, besides restoring BRM function." (PMID 25774356, 2014). "Four of the down-regulated genes were known cancer genes: KAT2B (from the Ade sequence only), BCL2, IQGAP2 (from Ade & IBD), and PMT (from IBD only)." (PMID 23799036, 2013). "Notably, KAT2B co-acetylates PLK4 with KAT2A at K45/K46 sites, suppressing its kinase activity to prevent centrosome amplification leading to cancer-associated chromosomal instability." (PMID 40495188, 2025). "The role of KAT2B in cancer depends on the cancer background." (PMID 34149798, 2021). "KAT2B low expression mechanism in cancer tissues still needs to be resolved." (PMID 34130593, 2021). "Above findings presented that KAT2B might be the tumor biomarker and anti-cancer target in different types of tumors." (PMID 34130593, 2021). "KAT2B also plays a role in the development and progression of cancer." (PMID 33224957, 2020). "KAT2B interactions with most of the lncRNAs from our list shows that these lncRNAs may play a major role in epigenetic regulation in cancers, since KAT2B protein is involved in lysine acetyltransferase activity in case of histone molecules." (PMID 30809433, 2019).
cancer (continued). "Besides, due to downregulated KAT2B expression in UCEC, we hypothesized that KAT2B might be an anti-cancer gene in UCEC." (PMID 39901144, 2025). "As far as we know, this study is the first to prove that Celastrol exerts anti-cancer effects in UCEC and KAT2B acts as a potential target of Celastrol." (PMID 39901144, 2025). "Thus, it is possible that some mechanisms of KAT2B may be cancer-specific or contexture-dependent." (PMID 38641672, 2024). "Specifically, HDAC4, HDAC5, KAT2B, NCOA1, SIRT1, and SIRT4 had lower expression in tumor tissues across 14, 12, 18, 17, 16, and 12 cancer types, respectively." (PMID 39906742, 2024). "This revealed a set of genes shared with human eTreg cells from affected sites in JIA, RA, and cancer including BATF, VDR, MICAL2, TOX2, KAT2B, PFKFB3, and IL12Rβ2." (PMID 33976194, 2021). "Last but not least, beyond cancer cell lines, we also knocked down KAT2B in a TNBC patient-derived organoid cell line and observed impaired mammosphere-forming ability, which is recapitulated by NELF-E KD." (PMID 37117180, 2023). "In addition, hsa-mir-106b-5p also targets genes that play an important role in immunity such as APP, VEGFA, KAT2B, MAPK8, and AGO1 and this miR-mRNA binding allows post-transcription disruption of these genes to influence cancer development." (PMID 33773548, 2021). "In addition to H3K9 acetylation, both Kat2a and Kat2b acetylate other non-histone substrates in various aspects of development and disease, including brain development and cancer." (PMID 30424580, 2018). "Hence, it may be more clinically appropriate to restore BRM function and its ability to inhibit growth by simply targeting KAT2B activity, rather than to silence BRM and risk the loss of BRM’s other anti-cancer functions." (PMID 25774356, 2014). "This analysis also revealed a number of epigenetic oncogenes (KDM1A, HDAC1, TDG) and tumor suppressors (KAT2B, PRDM5, DUSP1, EYA4) which did not correlate significantly with any of the others, suggesting that these may affect cancer DNAm patterns independently of each other." (PMID 26169266, 2015).
tumor (81 papers, 2002 to 2025). "Acetylation regulators, particularly KAT2B and HDACs, also support tumor growth and represent viable drug targets." (PMID 40508013, 2025). "The current study provides the first evidence that the histone acetyltransferase KAT2B is an important tumor-suppressive molecule in CCA." (PMID 38641672, 2024). "By immunohistochemical analysis, we found that the tumor cells with KAT2B overexpression showed decreased staining for the cell proliferation marker Ki67." (PMID 38641672, 2024). "The CCA tumors with KAT2B overexpression exhibited significant decrease in tumor size and tumor weight when compared to the control tumors." (PMID 38641672, 2024). "KAT2B is a member of the lysine transferases that are responsible for the acetylation of a broad range of proteins that can function as tumor suppressors or oncogenes." (PMID 37266381, 2023). "First, examination of our RNA-sequencing data revealed that of the 14 known HATs, the EP300 (KAT3B) and KAT2B transcripts showed uniformly enhanced expression in radiated tumor cells at both 2 and 7-days post-treatment." (PMID 36261421, 2022). "We reasoned that KAT2B might exert its tumor-suppressing function through upregulation of tumor-inhibitory genes in human CCA." (PMID 38641672, 2024). "This study provides the first evidence for an important tumor inhibitory effect of KAT2B in CCA through regulation of NF2-YAP signaling and suggests that this signaling cascade may be therapeutically targeted for CCA treatment." (PMID 38641672, 2024). "This study provides the first evidence for an important tumor inhibitory effect of KAT2B in CCA." (PMID 38641672, 2024). "Compared with normal tissues, the expression of CNV-amplified HA regulators was significantly increased in tumor tissues (e.g. HDAC3 in KIRC), while the expression of CNV-deficient HA regulators was significantly decreased (e.g. KAT2B, HDAC11 and PBRM1 in KIRC)." (PMID 37553641, 2023). "Previous studies have revealed the relationship between KAT2B and tumor occurrence and development." (PMID 36814797, 2023). "Among them, the expression of HDAC6 and KAT2B decreased in tumor tissue, while the rest increased." (PMID 36124029, 2022). "In recent years, relationship between KAT2B and tumor development has been gradually revealed." (PMID 34130593, 2021). "However, tumors eventually overcome KAT2A/KAT2B degradation, suggesting that more complete KATA2A/KAT2B degradation may be necessary for tumor regression or that SAGA inhibition may require combinatorial therapies." (PMID 38820154, 2024). "This is consistent with a recent report that targeting KAT2A/KAT2B with a PROTAC degrader, GSK-699, suppresses NB tumor growth." (PMID 40274766, 2025). "In acetylation, the enzyme KAT2B stabilizes the PAX3-FOXO1 fusion protein, promoting tumor progression." (PMID 40508013, 2025). "This leads to increase KAT2B-mediated ATIC acetylation to deactivate its enzymatic activity, reduced cellular purine biosynthesis, and tumor growth inhibition." (PMID 36750554, 2023). "KAT2A, SP140 and BRD9 protein expression was higher in tumor tissues, and SMARCA2, BRPF3, KAT2B and EP300 protein expression was lower in the tumor tissues." (PMID 34149798, 2021). "KAT2B is markedly overexpressed in FP-RMS tumor samples, and its genetic silencing or pharmacological inhibition reduces PAX3-FOXO1 protein levels, leading to decreased cell proliferation and impaired tumor growth in xenograft models." (PMID 40508013, 2025). "Similarly, KAT2B (PCAF) is overexpressed in TGCT and potentially promotes tumor progression by acetylating and activating the androgen receptor (AR)." (PMID 37569569, 2023). "Second, we found that KAT2B was higher in NPC tumor tissues than in their adjacent nontumor tissues." (PMID 33330099, 2020).
tumor (continued). "P300/CBP-associated factor (PCAF), also named lysine acetyltransferase 2B (KAT2B), is a HAT that mainly acetylates H3 histones, as well as a number of non-histone proteins that coordinate carcinogenic and tumor suppressive processes (Wang LT." (PMID 34880761, 2021). "For this purpose, SG231 cells or HuCCT1 cells with or without stable overexpression of KAT2B were injected subcutaneously into the flank of SCID mice and the animals were monitored for tumor growth." (PMID 38641672, 2024). "Only for five genes, namely KAT2A, SMARCA4, BAZ1A, ATAD2 and TRIM28, we observed consistently higher levels and for two genes—KAT2B and SMARCA2—lower levels, respectively, regardless of the tumor type." (PMID 35049055, 2022).
cardiovascular diseases (6 papers, 2016 to 2022). "KAT2B (lysine acetyltransferase 2B) is an important HAT epigenetic factor in the TGF-β signaling pathway and alteration in this gene has been associated with the etiology of cardiovascular diseases." (PMID 33803261, 2021). "KAT2B is an important histone acetyltransferase epigenetic factor in the TGF-β signaling pathway, and alteration in the gene is associated with the etiology of cardiovascular diseases." (PMID 32239175, 2020).
infection (4 papers, 2012 to 2020). The state of being infected such as from the introduction of a foreign agent such as serum, vaccine, antigenic substance or organism. "We found collectively among SP-A variants several genes such as AKT1, BTK, CCL9, PPARG, and RELA to exhibit higher expression in females, whereas, CFLAR, C1QC, LSP1, CKAP2, KAT2B, TACC2, and RCC2 exhibited higher expression in males after infection." (PMID 32670284, 2020). "The female mice exhibited higher expression levels of AKT1, BTK, CCL9, and LSP1 (KO, 1A0), PPARG (KO, 1A0, and 6A2), CFLAR, and ERP44 (1A0, 6A4), CCL9 (KO, 1A0, and 6A4), RCC2, and RELA (KO), KAT2B (6A2) and FKBP5 (1A0, 6A2, and 6A4) compared to males in response to infection." (PMID 32670284, 2020). "However, in response to infection, male mice exhibited higher expression levels of CFLAR, and FKBP5 (KO, 1A3), AKT1, and CCL9 (1A3, 6A2), C1QC (6A2), LSP1 (1A3, 6A2, and 6A4), CKAP2, and KAT2B (KO), TACC2 (1A0), RCC2 (1A3, 6A2), PPARG (1A3, 6A4), and ERP44 (6A2) compared to females." (PMID 32670284, 2020).
genetic disease (2 papers, 2018 to 2022). "KAT2B has previously not been associated with any genetic disease." (PMID 29768408, 2018). "These genetic disorders are prone to be modeled on D. melanogaster, since the fruit fly genome contains the hu li tai shao (hts) ortholog for ADD1 (adducin-α), ADD2 (adducin-β) and ADD3, and Gcn5 acetyltransferase (Gcn5) paralog for KAT2A and KAT2B." (PMID 35269756, 2022).
heart disease (2 papers, 2018 to 2024). "Recent reports indicate that Kat2b is a susceptibility gene for heart disease, and Kat2a is involved in the intracellular lipid accumulation observed in cardiac mesenchymal stromal cells in patients with arrhythmogenic cardiomyopathy." (PMID 39728461, 2024). "Additionally, another study identified Kat2b as a susceptibility gene for kidney and heart disease in ADD3-associated disorders." (PMID 39728461, 2024). "Altogether, our studies describe the expansion of the phenotypic spectrum in ADD3 deficiency associated with a homozygous likely pathogenic KAT2B variant and thereby identify KAT2B as a susceptibility gene for kidney and heart disease in ADD3-associated disorders." (PMID 29768408, 2018).
neurodegenerative disease (2 papers, 2020 to 2023). A disorder of the central nervous system characterized by gradual and progressive loss of neural tissue and neurologic function. "In summary, using an unbiased approach, we identified KAT2B and its inhibitor, L-Moses, as potential therapeutic targets for neurodegenerative diseases." (PMID 36894612, 2023).
kidney diseases (1 paper, 2018). "To address the phenotypic effects of the ADD3 and KAT2B knockdowns, we analyzed adhesion and migration, which are processes typically affected in kidney diseases such as SRNS." (PMID 29768408, 2018).
KAT2B also shares sentences with these, for which no sentence is quoted: lung adenocarcinoma (9 papers); colon cancer (5); cardiac hypertrophy (4); osteosarcoma (4); pancreatic cancer (4); colorectal tumor (3); renal fibrosis (3); alveolar rhabdomyosarcoma (2); Alzheimer disease (2); bladder cancer (2); fibrosis (2); Glucose intolerance (2); heart failure (2); Insulin resistance (2); memory impairment (2); metabolic syndrome (2); ovarian carcinoma (2); Stroke (2); acute monocytic leukemia (1); acute pancreatitis (1); acute promyelocytic leukemia (1); adenoma (1); AIDS (1); Arthritis (1); Autoimmunity (1); bone cancer (1); brain cancer (1); breast tumours (1); calculus (1); chronic gastritis (1).
A further 50 diseases each share a sentence with KAT2B in 1 paper.